BRCA1 (BRCA1 DNA repair associated)
Diseases named in the same sentence as BRCA1 in open-access papers (continued):
Sharing a sentence is not in itself a finding about the gene and the disease.
ovarian carcinoma (continued). "Ten out of 12 BRCA1 300T>G-carriers had no first- or second-degree relative with breast and/or ovarian cancers whereas in the group of 17 BRCA1 5382insC-carriers only four had negative family history." (PMID 22395474, 2012). "Though a subset of breast and ovarian cancers are associated with germline BRCA1 or BRCA2 mutations, the majority are sporadic and do not have BRCA1 or BRCA2 mutations." (PMID 22792303, 2012). "In this study, we revealed that, in Polish population, 51% of BRCA1-positive patients with ovarian cancer had negative family history of breast and/or ovarian cancer among I° and II° degree relatives." (PMID 22395474, 2012). "The consequences of defective homologous recombination (HR) are not understood in sporadic ovarian cancer, nor have the potential role of HR proteins other than BRCA1 and BRCA2 been clearly defined." (PMID 22253870, 2012). "Clinical evidence suggests that the use of PARP inhibitors is not restricted to BRCA1 or BRCA2 mutated cancers, but that it also targets non-BRCA mutated ovarian cancer and can be useful in combination therapy." (PMID 24970153, 2012). "This marked reduction in cost will enable BRCA1 and BRCA2 mutation detection to be more widely used especially for those who have a positive family history for breast or ovarian cancer but who do not meet current algorithms for mutation testing." (PMID 21702907, 2011). "Surprisingly, no ovarian cancer has so far occurred even among BRCA1/2 carriers, given the fact that the age of these women now without oophorectomy is 38–55 years." (PMID 20234365, 2010). "Identification of BRCA1 and BRCA2 has improved clinical management of some individuals with hereditary breast and ovarian cancer, but personalized care is not yet available for mutation carriers." (PMID 21037853, 2010). "Examples of these genes are BRCA1 and BRCA2 in breast and ovarian cancers." (PMID 20111735, 2010). "In both cases, ovary-specific conditional inactivation of Brca1 led to the development of pre-neoplastic or benign epithelial lesions in the ovary, but in neither case were invasive ovarian cancers observed." (PMID 20046879, 2009). "Moreover, the literature also suggests that PPP1CB is a discriminator gene between BRCA1-mutant and BRCA2-mutant tumors for both breast and ovarian cancers." (PMID 19695104, 2009). "This suggests that among BRCA1 carriers, there are familial genetic modifiers for breast, but not for ovarian cancer." (PMID 19401704, 2009). "Some molecules, such as BRCA1, soluble Fas levels, Death Receptor 4 and TNF receptor 2 (TNFR2), EF24, and trophinin, have been shown to correlate with cisplatin resistance in human ovarian cancer." (PMID 19293794, 2009). "Women with early-onset triple-negative breast cancer are candidates for genetic testing for BRCA1, even in the absence of a family history of breast or ovarian cancer." (PMID 19298662, 2009). "While a number of recent studies have characterized the expression profiles of miRNA in ovarian carcinomas including high grade serous carcinomas, none has examined the miRNA levels of high grade serous carcinomas with differing BRCA1/2 abnormalities." (PMID 19798417, 2009). "For example, patients with non-functional (mutated) BRCA1 or BRCA2, associated with hereditary breast and ovarian cancer, respond better to platinum chemotherapy owing to an increased sensitivity to DNA damage-induced cell death." (PMID 18349819, 2008). "To exclude the possibility of missed BRCA1 mutations among non-BRCA1/BRCA2 families, we conducted the same analysis after excluding families with ovarian cancer cases, but this did not alter the results." (PMID 18275599, 2008). "The estimate of ovarian cancer was also very similar with risks to 70 years of 60% for BRCA1 carriers and 33% as opposed to 27% for BRCA2 carriers." (PMID 18513387, 2008). "All of the 3 ovarian cancer cell lines, SKOV3, A2780 and A2780/CDDP, expressed endogenous BRCA1." (PMID 19690636, 2007).
ovarian carcinoma (continued). "It has recently been reported that reduced expression of BRCA1 is also common in sporadic ovarian carcinoma via its promoter hypermethylation, and that ovarian carcinoma patients negative for BRCA1 expression showed favorable prognosis." (PMID 19690636, 2007). "Higher frequency of BRCA1 and BRCA2 germ-line mutations were found in Ashkenazi Jewish breast and ovarian cancer patients regardless of family history." (PMID 17233897, 2007). "In people who do not have BRCA1 or BRCA2 gene mutations, the encoded proteins prevent breast/ovarian cancer." (PMID 17683622, 2007). "Our study showed that BRCA1 suppression affected neither the cell proliferation nor the cell cycle of ovarian cancer cells." (PMID 19690636, 2007). "In the present study, BRCA1 was specifically methylated in ovarian cancer, but not in the other two cancers." (PMID 16928264, 2006). "These preliminary data suggest that genomic rearrangements in BRCA1 do not have a major contribution in Belgian breast/ovarian cancer families." (PMID 15026808, 2004). "More recently, it has been reported that the expression of a truncated BRCA1 mutant with a dominant-negative activity modifies chemosensitivity in a mouse ovarian cancer cell line." (PMID 12698198, 2003). "Retroviral transfection of wild-type BRCA1 inhibits growth of breast and ovarian cancer cells in vitro but not those derived from colon or lung." (PMID 12698194, 2003). "However, not all cases of HBOC can be attributed to BRCA1 and BRCA2, as more than 20 other genes have been associated with an increased risk of familial breast and/or ovarian cancer." (PMID 40648909, 2025). "Ovarian cancer cells lacking BRCA1 have been reported to be more sensitive to AF therapy." (PMID 39857448, 2025). "Furthermore, though CDK12 inactivation in the Skov3 ovarian cancer cells showed some preferential downregulation of long genes overall, BRCA1 and BRCA2 protein were not affected." (PMID 39071291, 2025). "Since April 2020, BRCA1/2 genetic testing has been covered by the national health insurance system in Japan for the diagnosis of hereditary breast and ovarian cancer (HBOC) in patients with breast cancer who meet specific criteria and in all with ovarian cancer." (PMID 40900191, 2025). "Current guidelines recommend prophylactic adnexectomy for BRCA1/2 carriers at specific ages, but early-onset ovarian cancer remains a possibility, and many patients may never develop cancer." (PMID 40303993, 2025). "Additionally, when considering a family history of ovarian cancer, BRCA1 showed a high odds ratios of 8.96, whereas BRCA2 did not exhibit such a significance compared to BRCA1." (PMID 40323562, 2025). "Based on the role of USP4 in stabilizing BRCA1, we infer that loss or aberrant expression of USP4 may play a role in non-familiar breast and ovarian cancer and could correlate with the altered BRCA1 level." (PMID 38734703, 2024). "The Lambda model estimates the probability that an Ashkenazi Jewish woman is a BRCA1/BRCA2 PGV carrier based on a point system, considering personal family history, whether she is a first-degree or second-degree relative with BC and ovarian cancer, age at diagnosis, and bilateral BC in the proband." (PMID 38672070, 2024). "Indeed, because of that, one can create the risk function for patients (with or without BRCA1/BRCA2 mutations) related to their age only and assess the risk of breast or ovarian cancer for individuals." (PMID 38279352, 2024). "In conclusion, we hereby assign PAR2 as part of the gene signature which may serve as a predictor of ovarian cancer, highly expressed in the FTs of BRCA1/2 patients as opposed to there being none in normal tissues of FT." (PMID 38275417, 2024). "Not all individuals with BRCA1/2 PVs/LPVs will develop breast or ovarian cancer." (PMID 39796639, 2024).
ovarian carcinoma (continued). "However, not all cases of HBOC can be assigned to BRCA1 and BRCA2, as more than 20 other genes have been associated with an increased risk of familial breast and/or ovarian cancer." (PMID 38504328, 2024). "Similarly, the activation of the noncanonical Wnt/β-catenin signaling in BRCA1-null ovarian cancer cells can confer proliferative and metastatic advantages." (PMID 39028933, 2024). "However, it is important not to forget that BRCA1 and BRCA2 mutations are not very common, representing only a small fraction of the overall burden of ovarian cancer." (PMID 38391958, 2024). "When the RR was assumed to be independent of age, the estimated BRCA1 breast and ovarian cancer RRs (95% CI) were 15.6 (12.6–19.4) and 39.8 (29.6–53.3), respectively, and the estimated BRCA2 breast and ovarian cancer RRs (95% CI) were 10.3 (8.3–12.7) and 6.8 (3.9–11.9), respectively." (PMID 38333895, 2024). "Interestingly, in our model, we observed that Wnt3A preferentially activates the noncanonical Wnt signaling pathway in BRCA1-null ovarian cancer cells." (PMID 39028933, 2024). "Similarly, in September 2020, the Ministry approved niraparib as a maintenance treatment for patients with newly diagnosed, platinum-sensitive epithelial ovarian cancer, regardless of BRCA1 or BRCA2 status." (PMID 39590126, 2024). "While genetic factors are known to play a significant role in their development, specifically mutations in the breast cancer 1 (BRCA1) and breast cancer 2 (BRCA2) genes, it is important to note that not all breast and ovarian cancer patients carry these specific mutations." (PMID 38660159, 2024). "Family history information was not available from the COG cohort and thus we could not determine if the patients who had germline variants in BRCA1, BRCA2, or PALB2 had a family history of breast or ovarian cancer." (PMID 38110397, 2023). "Notably, their selection included patients from families affected by breast and ovarian cancer without a germline BRCA1 or BRCA2 mutation, while our selection was focused on the presence of tumor BRCA1 promoter hypermethylation." (PMID 36112334, 2023). "Of the 77 ovarian cancer cases aged <30 years, no BRCA1/2 PV was identified." (PMID 36894311, 2023). "Owing to its functional overlap with ATM, a DDR kinase already implicated in BC susceptibility, ATR has been previously tested as a potential candidate gene in two breast and ovarian cancer cohorts of respectively 126 and 54 patients without alterations of BRCA1/2." (PMID 36749285, 2023). "The purpose of our study was to identify the mutational spectrum of HBOC in a cohort of 4630 French probands with an indication for HBOC gene analysis and to determine the value of retesting BRCA1/2 negative cases using an expanded panel of breast and ovarian cancer genes." (PMID 37444530, 2023). "We found that the risks for breast and ovarian cancers in the female relatives of BRCA1 and BRCA2 carriers were significantly higher than non-carriers, and the risks for pancreatic and prostate cancers in male relatives of BRCA2 carriers were also significantly increased." (PMID 36861435, 2023). "Moreover, BRCA1 or BRCA2 mutations and a familial history of conditions such as hereditary nonpolyposis colorectal cancer also increase the risk of ovarian cancer; therefore, BRCA genetic testing is recommended for all ovarian cancer patients." (PMID 36312861, 2022). "Ovarian cancer cells with BRCA1 splice isoforms lacking exon 11 may be clonally selected under PARPi treatment." (PMID 35681784, 2022). "By plotting the sensitivity and specificity of classifying BRCA1/2 biallelic alteration vs. wild type using genomic LoH, the authors found a cutoff of >17.6% genomic LoH for BTC, which is very close to the >16% genomic LoH which was used in the ARIEL trial of rucaparib in ovarian cancer." (PMID 35626165, 2022).
ovarian carcinoma (continued). "However, extreme genome instability caused by these mutations did not result in more obvious apoptosis in the BRCA1-defective ovarian cancer patients than that in patients with normal BRCA1." (PMID 35517499, 2022). "Although PARPis were initially approved only for cancer patients with underlying defects in DNA damage repair, Niraparib has been recently approved as first-line maintenance therapy for advanced ovarian cancer in adults who responded to platinum-based chemotherapy, regardless of BRCA1/2 status." (PMID 36324587, 2022). "Thus, our study provides a scientific rationale for using Niraparib not only in ovarian cancer but also in PDAC patients regardless of their BRCA1/2 status." (PMID 36324587, 2022). "Therefore, NUSAP1 in ovarian cancer may participate in HRR by regulating the levels of ATR and BRCA1/2; thus, low expression of NUSAP1 in ovarian cancer implies sensitivity to PARP inhibitors." (PMID 35739489, 2022). "In 2017 to 2018, niraparib, olaparib and rucaparib have been approved for maintenance therapy in patients with platinum-sensitive ovarian cancer due to the observations that PARPi maintenance therapy significantly improves the PFS of patients with ovarian cancer regardless of BRCA1/2 status." (PMID 36284291, 2022). "In the PAOLA-1 phase 3 trial (NCT02477644), patients suffering from platinum-responsive ovarian cancer classified as HRD-positive based on the HRD score (≥42; Myriad myChoice® CDx) demonstrated better response to olaparib even when no BRCA1/2 mutations were present." (PMID 36077694, 2022). "Germline BRCA1 and BRCA2 PSVs may be prevalent in up to 20% of epithelial ovarian cancer." (PMID 34930165, 2021). "In order to include a BRCA1 defective control, we generated a stable, silenced BRCA1 402.91 liposarcoma cell line (402.91 shBRCA1) and we completed the panel with BRCA1 defective (IGROV-1 and OVCAR-8) and BRCA1 proficient (A2780 and UWB 1.289_BRCA1) ovarian cancer cell lines." (PMID 34944915, 2021). "BRCA1/2 germline mutations are most commonly seen in breast and ovarian cancer patients who benefit from treatment with PARP inhibitors (PARPis) or platinum compounds, but BRCA1-Δ11q splice variants lacking the majority of exon 11 contribute to therapeutic resistance." (PMID 34722250, 2021). "Besides, another two PARP inhibitors, niraparib, and rucaparib have been granted approval in the maintenance setting of ovarian cancer, regardless of BRCA1/2 status." (PMID 33800556, 2021). "However, reports also show that the combination of metformin and olaparib does not induce marked apoptosis in BRCA1-intact ovarian cancer cells, although cell-cycle analysis revealed a significant S-phase arrest." (PMID 34638899, 2021). "Of note, heterozygous BRCA1 inactivation results in genomic instability in nontumorigenic breast epithelial cells, and heterozygous mutations in BRCA1 and BRCA2 have been shown to contribute to development of HGSC in an ovarian cancer mouse model." (PMID 33922503, 2021). "Inherited mutations in the BRCA1 and BRCA2 genes and the Lynch syndrome (hereditary nonpolyposis colorectal cancer) have been closely associated with a highly increased risk of developing ovarian cancer." (PMID 34440232, 2021). "At the tested drug concentrations, 3-AB showed no significant cytostatic or cytotoxic effects, while olaparib generated cytostatic and no cytocidal effects against the BRCA1 mutated UWB1.289 and a lower cytostatic potential against the OVCAR-3 ovarian cancer cells." (PMID 34440232, 2021). "Indeed, a preclinical study showed that the PARPi talazoparib exquisitely synergized with guadecitabine, proving to be an effective combination therapy to treat breast and ovarian cancers irrespective of their BRCA1/2 status." (PMID 33470989, 2021).
ovarian carcinoma (continued). "Separately, the clinic files of 599 female carriers without a personal history of breast/ovarian cancer who underwent BRCA1/2 predictive genetic testing and received their results pre- and post-guideline were audited to ascertain the risk management advice given by health professionals." (PMID 33836815, 2021). "CA125 showed higher sensitivity than the BARD1 261-sample-fitted model for OC with or without BRCA1/2 or BARD1 mutations, presumably this reflects that those sub-groups contained more late-stage ovarian cancers, which are better detected by CA125 than early-stage cancers." (PMID 34201956, 2021). "Still, currently there is no clear rationale regarding which PARPi to use, for which ovarian cancer patients beyond FDA endorsement of olaparib, rucaparib or niraparib when a mutation is present in BRCA1 or BRCA2 after first-line platinum-based chemotherapy or as maintenance therapy." (PMID 34445211, 2021). "In this study 489 women with a BRCA1 or BRCA2 mutation aged from 25 to 65 years, who had never had breast or ovarian cancer, were screened annually with breast magnetic resonance imaging (MRI) in addition to mammography and were followed for an average of 13 years (range: 9 to 23 years)." (PMID 33238387, 2020). "And although ovarian cancer has a high hereditary portion, the frequency of genetic risk factors such as hereditary non-polyposis colorectal cancer (HNPCC)/or Lynch syndrome, BRCA1 and BRCA2 mutant genes are unknown." (PMID 32499531, 2020). "Interestingly, BRCA1 depletion-induced NNMT upregulation was shown to promote metabolic reprogramming of ovarian cancer cells, which sensitized ovarian cancer cells to agents that inhibit mitochondrial metabolism (VLX600 and tigecycline) and to agents that inhibit glucose import (WZB117)." (PMID 33193702, 2020). "In the absence of BRCA1 or BRCA2 protein function, the preferential use of error-prone DNA repair mechanisms leads to genomic instability, a peculiar feature of breast and ovarian cancers arising from BRCA mutations that may favor carcinogenesis." (PMID 32481735, 2020). "In patients without germline or somatic BRCA1/2 mutations in recurrence setting, the Personalised Medicine Commission recommends testing the other HRD and other ovarian cancer risk genes to identify patients eligible for clinical trials and cancer genetic counselling in the relatives." (PMID 33123697, 2020). "Notably, a recent study identified BRCA1, but not BRCA2, mutations to be associated with immunogenic phenotype in ovarian cancers." (PMID 31022191, 2019). "Indeed, BRCA1 and BRCA2 are the most common genes related to hereditary breast and ovarian cancers." (PMID 31412890, 2019). "Importantly, Evans and colleagues reported constitutional BRCA1 methylation in WBC from members of two families characterized by high incidence of breast and ovarian cancer, but testing negative for BRCA1/2 germline mutations." (PMID 31225507, 2019). "On the other hand, genetic mutation of PALB2 (another BRCA-Fanconi anemia ovarian cancer-associated gene), whose transcribed protein binds at BRCA1 and RBCA2 at the sites of DNA damage, has been associated with heredity of breast cancer syndrome, but not with ovarian cancer." (PMID 31366178, 2019). "Finally, duplication and translocation breakpoints were strongly enriched in early-replicated regions in CCN-HCC as compared with other HCC, but not in BRCA1-altered as compared with other breast and ovarian cancers." (PMID 30531861, 2018).